TLR4 (toll like receptor 4)
Diseases named in the same sentence as TLR4 in open-access papers (continued):
Sharing a sentence is not in itself a finding about the gene and the disease.
cardiovascular diseases (continued). "A deeper understanding of the genetic variability of TLR4 will enable us to better identification of biomarkers for early detection and prognosis, and also enhance the decision‐making process of treatments for cardiovascular diseases." (PMID 31328431, 2019). "Very few studies have examined the role of TLR4 in cardiovascular disorders." (PMID 25811788, 2015). "Our finding suggests that TLR4 signaling pathway and ER stress could be important pharmacological targets for treating some of the autonomic dysfunction in cardiovascular disease." (PMID 25811788, 2015). "Similar to humans, TLR4 is also involved in cardiovascular diseases in mice." (PMID 25071777, 2014). "Clarifying the interactions of these blood elements (platelets and leukocytes) in the setting of TLR4 activation might provide insight into how infection initiates or facilitates progression of cardiovascular disease." (PMID 21966536, 2011). "Collectively, these results identify an acute and rapid signaling mechanism by which sentinel-grade acute infection through TLR4 alters blood hemostasis and sustained leukocyte activation which may contribute to progression of cardiovascular diseases." (PMID 21966536, 2011). "However, the regulation of TLR4 expression in cardiovascular diseases remains elusive." (PMID 31328431, 2019). "Determination of the effector proteins involved and their responses may lead to the discovery of novel pathways downstream of TLRs and present TLR4 as a novel therapeutic target for the treatment of cardiovascular diseases and other pathological settings such as inflammatory disease." (PMID 29170605, 2017). "TLR4, a transmembrane protein in the TLR family, is highly expressed during cardiac injury and serves as a critical mediator of cardiac inflammation in cardiovascular disease progression." (PMID 40640887, 2025). "Within this complex pathological framework, Toll-like receptor 4 (TLR4), a key pattern recognition receptor in the innate immune system, has emerged as a central player in the pathogenesis of cardiovascular diseases." (PMID 40640887, 2025). "Herein we will discuss the role of TLR4 and AMPK in cardiovascular diseases and a possible relation between TLRs and AMPK as a novel therapeutic target." (PMID 36721803, 2023). "Indeed, significant overexpression of the Toll-like receptor 4 (TLR4) gene, the activation of interleukin-1 receptor-associated kinase 4 (IRAK4), in addition to numerous cathepsin proteases and matrix metalloproteinases were observed in MPS cardiovascular disease." (PMID 36556450, 2022). "Importantly, TLR4 expression has been reported to be strongly correlated with the severity of CAD, as reflected by the number of coronary stenoses, and may be a clinically useful biomarker of the risk of cardiovascular disease." (PMID 36204316, 2022). "The rs4986790 SNP in TLR4 has been shown to have little evidence of association between the Asp299Gly gene polymorphism and risks for incident myocardial infarction (Zee, Hegener, Gould, & Ridker, 2005) whereas the rs2770150 and rs10759931 SNPs have not been associated with cardiovascular disease." (PMID 31328431, 2019). "Both TLR4 and TLR2 have been shown to play a role in mediating repair and recovery in cardiovascular disease, and both also recognize the danger signal HMGB1." (PMID 26998496, 2016). "Combination therapies with Gabapentin and agents such as corticosteroids or TLR4 antagonists also warrant exploration, with careful attention to comorbidities like BBB disruption or cardiovascular disease, which may affect drug safety and response." (PMID 41007696, 2025). "Relevant investigations of the role of the HMGB1/TLR4 axis in cardiovascular diseases are not uncommon." (PMID 38456997, 2024).
cardiovascular diseases (continued). "Recent research results have led to a hypothesis that there may be a relation between TLR4 expression and 5' adenosine monophosphate-activated protein kinase (AMPK) signaling in various inflammatory conditions, including cardiovascular diseases." (PMID 36721803, 2023). "Although compelling studies show that HMGB1 and TLR4 play pivotal roles in the pathogenesis of cardiovascular diseases and inflammatory response, but there was no literature about HMGB1/TLR4 signaling contributes to atherogenesis induced by CUMS." (PMID 30881312, 2019). "Whether anti-TLR4 treatments would be effective in managing PAD remains to be investigated, but the suggestion represents a novel approach to treating patients with cardiovascular disease." (PMID 26998496, 2016). "In the subsequent multivariable analysis, we confirmed the absence of cardiovascular disease, low levels of IL-6 and PCT, and TLR4 rs4986790 AG/GG genotypes as independent predictors of potential hospitalization and reduction of severe or fatal disease course." (PMID 38433829, 2024).
infectious disease (91 papers, 2007 to 2026). A disorder directly resulting from the presence and activity of a microbial, viral, or parasitic agent in humans. "Overall, TLR4 exhibits context-dependent protective and pathogenic roles across infectious and non-infectious diseases, reflecting the complexity of its signaling in human health and disease." (PMID 41869302, 2026). "Molecular mechanisms reveal that HMGB1 binding and TLR4 signaling mediate cytokine release and tissue damage including caused infectious diseases." (PMID 35340325, 2022). "The aim of this article is to review in which infectious diseases there is an association of susceptibility or protection by the TLR4 SNP rs4986790." (PMID 36506333, 2022). "The most commonly associated infectious diseases in different countries for TLR4 SNP and susceptibility were those caused by viruses (6 researches, 85.71% in virus subgroup)." (PMID 36506333, 2022). "Due to their importance in generating an immune response in the fight against pathogens, polymorphic variants of TLR4, such as rs4986790, have great value in identifying the risk and defense of infectious diseases." (PMID 36506333, 2022). "TLR4 polymorphisms are differently distributed around the world, and they are attributed to evolutionary pressure from infectious diseases and the migration of mankind over time." (PMID 33557133, 2021). "TLR4 SNP rs4986790 is one of the most studied SNPs and its variant genotypes AG and GG are associated with several infectious diseases." (PMID 32967147, 2020). "Single nucleotide polymorphisms (SNPs) affecting the TLR4 function modulates the development and severity of infectious diseases." (PMID 29922617, 2018). "Lipopolysaccharide (LPS) signaling through Toll-like receptor-4 (TLR-4) has been implicated in the pathogenesis of many infectious diseases." (PMID 27064683, 2016). "Several investigators have studied the roles of TLR4 genetic polymorphisms in major infectious diseases, including TB." (PMID 25928077, 2015). "We performed a systematic literature review to address the potential association of 2 common TLR4 single nucleotide polymorphisms (TLR4 896 A>G, TLR4 1196 C>T) with infectious diseases." (PMID 24282567, 2013). "In previous studies variants in the TLR4 gene have been shown to be associated with infectious and non-infectious diseases but rather inconsistently." (PMID 21931695, 2011). "In this sense, the manifestation of infectious diseases may be related to mutations in the TLR4 gene due to the absence/presence of the mutant allele of SNPs, in addition to genetic, epigenetic, and environmental factors." (PMID 36506333, 2022). "However, the impairment of TLRs due to polymorphisms of TLR genes can alter the immune response to a wide variety of microbial ligands, including viruses, and polymorphisms in TLR2 and TLR4 have been linked to infectious diseases in humans." (PMID 32824985, 2020). "Besides, the protective role of AHCC® in infectious diseases seems to be related to its immunomodulatory properties by priming TLR-4 and TLR-2 and the associated TLR-4/MyD88 and NF-κB/MAPK signal transduction pathways." (PMID 31484389, 2019). "Our findings support the hypothesis that genetic polymorphisms of the TLR4 gene affect the host’s susceptibility to infectious diseases." (PMID 27339100, 2016). "The present study aims to reassess the association of TLR4 896 A>G and TLR4 1196 C>T with infectious disease susceptibility using the Generalized Odds Ratio (ORG), which can elucidate the magnitude and association of individual genotypes with susceptibility to disease." (PMID 24282567, 2013). "Toll-like receptor 4 plays a role in pathogen recognition, and common polymorphisms may alter host susceptibility to infectious diseases." (PMID 24282567, 2013). "There is a study which supports the notion that rare as well as common variants of TLR4 may be associated with infectious disease susceptibility." (PMID 19277200, 2009).
infectious disease (continued). "Summary of TLR4 polymorphisms associated with infectious diseases." (PMID 19277200, 2009). "We anticipate that this novel strategy will apply to the treatment of multiple infectious and non-infectious diseases in which HMGB1-mediated TLR4 signaling is a central driver of inflammation." (PMID 39699172, 2025). "Collectively, CPP-3a emerges as a potent TLR4-targeted immunomodulator with adjuvant potential for inflammatory and infectious diseases." (PMID 40710515, 2025). "While LPS can activate the TLR4 signaling pathway in both infectious and non-infectious diseases, the sources of LPS differ, and the resulting immune outcomes are not uniform." (PMID 39238498, 2024). "Conversely, in non-infectious diseases, TLR4 signaling activation occurs via endogenous ligands like damage-associated molecular patterns (DAMPs) and danger signals, released during tissue damage, stress, or chronic inflammation." (PMID 39238498, 2024). "Whereas TLR4 is a primary signal of the innate immune response pathway, which plays a key role in the defense mechanism against infectious diseases, evidence suggests that endotoxin is also recognized via TLR4 receptors." (PMID 39518951, 2024). "MyD88-dependent and -independent pathways exhibit differences in TLR4-related infectious and non-infectious diseases." (PMID 39238498, 2024). "The reports have provided a few examples that TLRs, interacting with endogenous ligands from the host, especially TLR4, are engaged in the process of infectious and non-infectious diseases." (PMID 37200915, 2023). "TLR4 regulates immune response not only against microbial components in infectious disease but also against endogenous ligands in the sterile inflammation process." (PMID 37251076, 2023). "Nevertheless, the impact of endogenous DAMPs on the TLR4 activity broadens the spectrum of pathophysiological conditions involving the TLR4-induced pro-inflammatory responses far beyond infectious diseases." (PMID 33057840, 2021). "Toll-like receptor 4 (TLR4) is a pattern recognition receptor mainly involved in the regulation of inflammation during infectious diseases." (PMID 34746034, 2021). "A comprehensive knowledge of the TLR4 trafficking pathways and the role of CD14 in these processes is key to understanding mechanisms regulating TLR4-induced inflammatory response in both infectious and non-infectious diseases." (PMID 33057840, 2021). "SNPs in the TLR2, TLR4 and TLR9 polymorphisms have been studied for altering the susceptibility and resistance to various inflammatory and infectious diseases." (PMID 29922617, 2018). "The potential application of Rn as an inhibitor of TLR-2 and TLR-4 activation provides a promising lead for drug development in infectious diseases induced by complicated microbial patterns." (PMID 26987407, 2016). "Of note, although IRF1 signals are essential for infectious diseases and for the inflammatory response of TLR4, IRF1, NF-κB2 and STAT2 were predicted to exhibit higher activation under TLR3 stimulation." (PMID 26159724, 2015). "TLR4 is part of a complex immune system network and plays a key role in protection as an important regulator of components present in many infectious diseases." (PMID 24025421, 2013). "For instance, mutations in TLR2, TLR4, TLR5 and IRAK4 have all been associated with increased risk to develop infectious diseases." (PMID 19859543, 2009). "TIRAP is a critical gene in the TLR2 and TLR4 signalling cascades and recent studies have investigated its role in a number of infectious diseases including TB." (PMID 19693265, 2009). "In addition, the reduced expression of TLR4 and HLA-DR, the first line of defense for pathogen recognition in infectious diseases, corroborates the idea of a state of immune incompetence created under citrate anticoagulation." (PMID 38474146, 2024).
infectious disease (continued). "The activation of the TLR4/MyD88/NF-κB signaling pathway has been shown to promote the secretion of immune factors and enhance dendritic cell (DC) antigen presentation, playing a crucial role in combating infectious diseases." (PMID 39749332, 2024). "In step, this dysfunctional stimulation of TLR4 is characterized by suppression of recognition and immune response to pathogens, generating an uncoordinated immune response and, consequently, in most cases, a poor prognosis to infectious diseases." (PMID 36506333, 2022). "As the pig industry faces a unique array of related pathogens, it is anticipated that the genotype of swine TLR4 could be of crucial importance in future strategies aimed at improving genetic resistance to infectious diseases." (PMID 29273011, 2017). "This has lead to the hypothesis that other genetic variations of TLR4 may change the function of the protein and alter the efficiency of the immune response to an infectious disease." (PMID 19277200, 2009). "Vaccines based on s-MVs may protect against not only TB but also other infectious diseases, such as those caused by gram-negative pathogens, in a TLR4-dependent manner." (PMID 40145097, 2025). "In this paper, we have demonstrated that chronic SCI patients without associated inflammatory and infectious diseases show functional impairment of circulating monocytes, with diminished TLR4 expression, increased LPS-induced TNF-α production and defective phagocytosis." (PMID 33451043, 2021). "The innate immune receptor toll-like receptor 4 (TLR4) has been recognized as the receptor on hematopoietic and non-hematopoietic cells for bacterial endotoxin (lipopolysaccharide, “LPS”), as well as for a variety of endogenous molecules that are released during inflammatory or infectious disorders." (PMID 23776545, 2013). "As a result of its early discovery as a TLR4-stimulating adjuvant, MPL became the first TLR agonist to gain approval for use in humans as part of vaccines against infectious diseases." (PMID 33499143, 2021). "Toll-like receptor 4 (TLR4) is an important pattern recognition receptor, which is expressed on cell membrane and plays an important role in infectious and non-infectious diseases." (PMID 32269523, 2020). "In conclusion, TLR4 anergy can occur in HEU infants without necessarily translating to increased vulnerability to infectious diseases." (PMID 29491865, 2018). "Previous studies demonstrated that TREM-1 on monocytes/macrophages could amplify the inflammatory effects in infectious diseases, and interaction between TREM-1 and TLR-4 could enhance the TLR-4 signaling pathway activity leading to multiple proinflammatory mediator secretion." (PMID 31885496, 2019). "Up-regulation of TLR4 and TLR10 in NEC neonates as compared to non-NEC preterm neonates is consistent with the key role played by these bacteria sensing molecules in infectious diseases." (PMID 26801768, 2016).
metabolic disorders (91 papers, 2010 to 2026). "Together, these results indicated that loss of TLR4 mitigated metabolic disorders in aged mice." (PMID 34740366, 2021). "We studied two polymorphisms (+3725G/C and 11350G/C) in the 3′ untranslated region (3′UTR) of the TLR4 gene that may alter its expression and their association with metabolic disorders related to systemic inflammation." (PMID 23239997, 2012). "In metabolic disease, this microbial endotoxemia triggers systemic inflammation via Toll-like receptor 4 (TLR4) and NF-κB signaling, contributing to insulin resistance and tissue damage." (PMID 41374093, 2025). "Taken together, the findings of this study indicate that TLR4 has potential as a novel target to prevent and treat metabolic diseases." (PMID 38275739, 2024). "The findings of this study indicate that TLR4 has potential as a novel target to prevent and treat metabolic diseases." (PMID 38275739, 2024). "TLR-4 is a key immunological pathway activated by bacterial lipopolysaccharides that produce pro-inflammatory cytokines, inducing metabolic disorders and promoting greater liver damage in patients with NAFLD." (PMID 38600992, 2024). "It has been reported that VLCFA-GM3 is an agonist of the TLR4 signal pathway and plays an important role in the pathogenesis of metabolic disorders through TLR4-mediated innate immune signals." (PMID 35770013, 2022). "In human monocytes, vitamin D suppresses the mRNA expression of Toll-like receptor 2 (Tlr-2) and Toll-like receptor 4 (Tlr-4) proteins, which are important regulators of metabolic inflammation during the development of metabolic disorders." (PMID 35859985, 2022). "FO and PO exhibit similar protective effects on metabolic disorders and inflammation through inhibiting TLR4 signaling in a manner dependent on MyD88." (PMID 34168108, 2021). "Prior studies have shown SFAs induce microgliosis and trigger TLR4/IKKβ/NF-κB pathways, resulting in the impaired metabolic disorder of the hypothalamus." (PMID 34750365, 2021). "In summary, the present study demonstrates that FO and PO have the similar protective effects on metabolic disorders and inflammation through inhibiting TLR4 signaling in a manner dependent on MyD88." (PMID 34168108, 2021). "Once in circulation, LPS elicits a potent inflammatory response via Toll-like receptor-4 (TLR-4) signaling, which has been implicated in the development of cardiovascular and metabolic disease." (PMID 34168615, 2021). "In conclusion, our findings would help clarify the pathophysiological roles of serum/ adipose GM3 species in TLR4 signaling, and the complex interplay between glycosphingolipid metabolism and innate immune signaling in metabolic disorders." (PMID 32378734, 2020). "Innate immune signaling via TLR4 plays critical roles in pathogenesis of metabolic disorders, but the contribution of different lipid species to metabolic disorders and inflammatory diseases is less clear." (PMID 32378734, 2020). "Potential molecular links between FFAs and metabolic diseases are the Toll-like receptors; FFAs trigger inflammatory responses via TLR4 promoting inflammatory gene expression by triggering NF-κB activation." (PMID 32089647, 2020). "Knockdown of TLR4 ameliorates insulin resistances and glucose tolerance, suggesting that TLR4 is a key therapeutic target for metabolic disorders." (PMID 33291425, 2020). "LPS from gram-negative intestinal microbiota is an early factor recruiting a signals through TLR4 to induce secretion of pro-inflammatory cytokines and then triggering metabolic diseases induced by a high-fat diet." (PMID 30863401, 2019). "An extensive literature review demonstrates a strong relationship between the TLR4 pathway and high-fat diet consumption in metabolic diseases." (PMID 31035535, 2019). "An extensive review of the literature showed a strong relationship between the TLR4 pathway and high-fat diet intake in metabolic disorders." (PMID 30037112, 2018).